EGFR (epidermal growth factor receptor)
Diseases named in the same sentence as EGFR in open-access papers (continued):
Sharing a sentence is not in itself a finding about the gene and the disease.
tumor (continued). "The identification of MET amplification in the patient’s tumor, a well-established mechanism of resistance to anti-EGFR therapy, led to the prescription of a combination of erlotinib and the MET inhibitor crizotinib." (PMID 29241554, 2017). "Tumor cells have access to circulating ligands that induce paracrine activation of EGFR, and in addition, some tumor cells produce augmented amounts of EGFR ligands, which initiate signaling in an autocrine fashion." (PMID 29268862, 2017). "It is thus likely that the EGFR gene copies in the tumor cells are present as extrachromosomal double minute (DM)-type micronuclei." (PMID 28148893, 2017). "The anti-tumor mechanisms depend on inhibition of EGFR- and IL-17RA-signaling and enhancement of anti-tumor immune responses." (PMID 29212184, 2017). "EGFR is one of the most important receptors of tumor cell growth via a variety of signaling pathways." (PMID 28628609, 2017). "The high affinity of antibodies to EGFR and the overexpression of EGFR in tumor cells lead to the agglomeration of gold nanoparticles in tumor zone." (PMID 29046833, 2017). "Remarkably, it has been demonstrated that the overexpression of epidermal growth factor receptor (EGFR), a member of the ErbB receptor family, is associated with lower local tumor control after radiotherapy and a shortened overall survival in HNSCC." (PMID 29214166, 2017). "We then used cDNA microarray gene expression data to examine the mRNA expression levels of COX-2 (204748_at)and EGFR (211551_at) in tumor biopsy specimens from 25 patients with IBC." (PMID 28978083, 2017). "Herein, we demonstrate that coactivation of EGF and EGFR drives tumor metastasis in a matrix metalloproteinase-9 (MMP-9)–dependent manner." (PMID 29029486, 2017). "EGFR-positive CTCs has been detected in a number of tumor types, such as breast, prostate, colorectal, and lung cancer." (PMID 29229933, 2017). "Using the MMTV-erbB-2 mouse model, it has been shown that treatments with EGFR-targeting gefitinib or lapatinib both significantly inhibited the formation of premalignant lesions in the mammary glands and delayed spontaneous tumor development." (PMID 28061785, 2017). "We also explored the sequence of cetuximab followed by anti-VEGF antibody versus bevacizumab followed by anti-EGFR antibody with respect to primary tumor location." (PMID 29285289, 2017). "EGFR targeted micelles loaded with the second generation PS phthalocyanine-4 (Pc 4) showed increased tumor cell selectivity and rapid intracellular PS uptake." (PMID 28218708, 2017). "A significant correlation was found between EGFR status and smoking history, pathology and tumor location." (PMID 28422710, 2017). "This reinforces that tumor IGFBP-3 expression is involved in driving EGFR-SphK1-dependent proliferation in TNBC cells, and should be evaluated as a possible biomarker of efficacy of the inhibitory drug combination." (PMID 28778177, 2017). "Further in vivo studies are warranted to explore the anti-tumour activity of tivozanib alone or in combination with EGFR inhibitors in chemoresistant EOC." (PMID 28383032, 2017). "We used a library of VHHs obtained by immunizing llamas with A431 human tumour cells that overexpress EGFR." (PMID 28772027, 2017). "Continuous decrease of tumor volumes was observed in the anti-EGFR-, anti-EGFR-GN- and anti-EGFR-GN+NIR-PTT-treated mice versus control." (PMID 29156817, 2017). "The objective of this current study was to develop a molecular vector that successfully recognizes and selectively binds to the L858R mutation of EGFR found in NSCLC cells, thus differentiating between tumor and healthy cells." (PMID 28611939, 2017). "We show that pharmaceutical inhibition of LOX disrupts this signalling pathway, reducing EGFR signalling and delaying tumour progression." (PMID 28416796, 2017). "Preclinical data suggest that resistance to anti-EGFR targeted therapies results from increased tumour angiogenesis." (PMID 28383032, 2017).
tumor (continued). "We first tested a panel of EGFR‐mutated cell lines for their ERK and AKT phosphorylation status, two key actors of the EGFR signaling pathway involved in the sensitivity of tumor cells to EGFR‐TKI." (PMID 28003335, 2017). "During the study period, 69 NSCLC patients were identified as having acquired resistance to EGFR-TKI therapy after previous tumor shrinkage." (PMID 29212495, 2017). "It was found that other tumor-specific proteins included plasma exosomal surface EGFR or leucine-rich alpha-2-glycoprotein (LRG1) in urinary exosomes, which were identified in lung cancer patients." (PMID 29282096, 2017). "In this study, we found that afatinib exhibited anti-tumor efficacy in vitro and in vivo by inducing apoptosis and blocking EGFR-mediated PI3K/AKT/mTOR signaling." (PMID 27902463, 2017). "Epidermal Growth Factor Receptor (EGFR), a tyrosine kinase receptor, is one of the main tumor markers in different types of cancers." (PMID 29228029, 2017). "The frequency of EGFR mutations and CT features of ground-glass opacity (GGO) content, tumor size, cavitation, air-bronchogram, lobulation, and spiculation were extracted." (PMID 28068946, 2017). "The pilot experiment with 68Ga-radiolabeled cetuximab allowed for identification of engrafted EGFR-expressing tumor cells in the bladder, and, furthermore, demonstrated the principal usability of radioimmunologic diagnostics of such tumors in the bladder." (PMID 29169339, 2017). "Current knowledge how tumor cells with EGFR gene copy number alterations in the primary tumor are related to metastases and recurrences in OSCC is limited." (PMID 28854970, 2017). "GE11 binds to Epidermal Growth Factor Receptor (EGFR), which is displayed by a number of tumours of epithelial origin." (PMID 28538671, 2017). "The high prevalence of EGFR/EGFRvIII overexpression as well as the tumor specificity of EGFRvIII makes EGFR/EGFRvIII attractive targets for generation of RITs." (PMID 28752098, 2017). "Analysis of their clinical characteristic revealed that the ectopic expression of lnc-EGFR correlated with tumour size in the HCC patients." (PMID 28541302, 2017). "For example, miR-27b can suppress growth, cell migration and invasion in tumor cells by targeting multiple tumor-related genes such as Sp116, EGFR and c-Met17." (PMID 28202938, 2017). "Among these proteins, the epidermal growth factor receptor (EGFR), hepatocyte growth factor receptor (Met) and cellular Src kinase (c-Src) are key regulators of tumor cell proliferation, survival and invasion." (PMID 28446239, 2017). "Since tumor lysis has been postulated to be the main source of ctDNA, a possible explanation for these seemingly discordant results is that pEGFRmut concentration reflects EGFR mutation abundance in tumor tissues, which in turn might entail higher sensitivity to EGFR-TKIs." (PMID 28061461, 2017). "It is also known that EGF promotes tumor angiogenesis, cell motility, and invasion, and that EGFR stimulates cell migration through receptor phosphorylation and subsequent activation of downstream signaling pathways." (PMID 28629170, 2017). "In the EGFR and ALK mutations, targeted therapy inhibits the growth of tumor cells by blocking the activity of tyrosine kinase." (PMID 28327204, 2017). "Compared to IgG, an anti-EGFR IgA2 antibody showed comparable and better anti-tumor efficacy in transgenic mouse xenograft models." (PMID 28952521, 2017). "This indicates that anti-EGFR-GN+NIR-PTT led to the most effective therapy for tumor regression through augmentation of the synergic mechanisms of anti-proliferation and apoptosis." (PMID 29156817, 2017). "Further to this, EGFR expression was heterogeneous resulting in a score of 0, but showing focal EGFR membranous positive tumor cells even within the same tumor glands (cases #8, #9)." (PMID 28199979, 2017).
tumor (continued). "Transcriptional regulation of genes involved in cell proliferation, tumor progression, inflammation and chemo-resistance are among the main functions of nuclear EGFR." (PMID 28415726, 2017). "Again, this enhanced tumor selectivity is indicative of a strong avidity mediated by cross-binding of EGFR and HER2 antigens on double-positive tumors." (PMID 28067257, 2017). "Sortilin is therefore a regulator of EGFR intracellular trafficking that promotes receptor internalization and limits signaling, which in turn impacts tumor growth." (PMID 29084952, 2017). "The predictive value of RAS WT status from plasma and tumor determination was analyzed in the subset of patients who received anti-EGFR plus the irinotecan backbone in second- or third-line therapy (N = 52)." (PMID 28368441, 2017). "These synergistic anti-tumor effects further support a role for IGF-1R as a mediator of resistance to anti-EGFR agents." (PMID 28002810, 2017). "Erlotinib has activity against epidermal growth factor receptor (EGFR) with the function of inhibiting tumor proliferation and differentiation." (PMID 29240712, 2017). "Viloria-Petit and colleagues have observed the acquired resistance of tumor cells to anti-EGFR monoclonal antibodies associated with increased levels of VEGF, accompanied by an increase in angiogenic potential in vitro and tumor angiogenesis in vivo." (PMID 29285236, 2017). "Previous studies of tumor biopsies found that a minority of patients (5–15%) exhibited multiple mechanisms of EGFR inhibitor resistance." (PMID 28431544, 2017). "Consistent with our in vitro data, the level of tumor selectivity was inversely proportional to the reduced intrinsic affinity to EGFR." (PMID 28067257, 2017). "Use of an OXPHOS uncoupling agent together with an EGFR inhibitor is a good combination to achieve anti-tumor thermal therapy, especially in body regions where less controllable extraneous heating therapies are contraindicated." (PMID 28915593, 2017). "Our findings are consistent with recent studies suggesting that EGFR signaling pathways are involved in tumor angiogenesis, especially through the upregulation of VEGF." (PMID 28288572, 2017). "Although erlotinib treatment did not inhibit basal growth of PC-10 cells in vitro, it did suppress the growth of PC-10 tumour xenografts in vivo and EGFR phosphorylation in the tumour." (PMID 28642617, 2017). "The two PDECX models with EGFR gene amplification were most sensitive to theliatinib treatment with rapid and robust tumor regression." (PMID 28881608, 2017). "EGFR amplification leads to a unique conformation of the EGFR protein that exposes a tumor-specific binding site for depatux-m." (PMID 29075855, 2017). "We also measured the expression of Ki67, EGFR, E-cadherin and N-cadherin in the xenograft tumor tissues using immunohistochemistry." (PMID 28825720, 2017). "First, we examined how EGFR signaling impacts HLA class I membrane expression in these tumor cell lines." (PMID 29056908, 2017). "Antibodies that target and bind the extracellular domain of EGFR, such as cetuximab, have shown decreased tumor growth and increased survival in mouse xenograft models but again, did not demonstrate a survival benefit in patients." (PMID 29075855, 2017). "Expression of EGFR was observed in 37% of tumours with low and 40% of tumours with high malignant potential." (PMID 28377929, 2017). "In a paracrine loop intra-tumoral macrophages secrete EGF, which binds to the EGFR on tumor cells, promoting their invasion." (PMID 28970798, 2017). "In this report, a PC-10 tumour treated with ChMS-1 antibody showed a decrease in EGFR signal in vivo." (PMID 28642617, 2017).
tumor (continued). "In many tumors EGF is produced either by the tumor cells themselves or is available from surrounding stromal cells, leading to constitutive EGFR activation." (PMID 28038470, 2017). "Patients with positive plasma ctDNA tests and negative tissue results had shorter progression-free survival compared to patients with EGFR p.T790M detected in both their tumour tissue and plasma ctDNA." (PMID 28840321, 2017). "In human GBM tumor sections, we observed an inverse correlation between RanBP6 and EGFR protein levels and RanBP6 knockdown upregulated EGFR expression in the human GBM cell line LN18, consistent with earlier results in HEK-293T cells and MEFs." (PMID 29229958, 2017). "Previous studies showed an increase in HLA class I cell surface expression in tumor cell lines treated with anti-EGFR agents." (PMID 29056908, 2017). "Tumor specificity and transduction efficiency were examined in high EGFR-expressing LS174T metastases by non-invasive imaging using 18F-tetrafluoroborate (18F-TFB) as novel NIS PET tracer." (PMID 29190908, 2017). "EGFR expression is elevated in many tumours, which correlates with poor clinical outcome in some cases." (PMID 28320414, 2017). "Cell-free circulating tumor DNA (cftDNA) was extracted from plasma and the quantitative analysis of EGFR ex19del, p.L858R and p.T790M was performed by digital droplet PCR." (PMID 29156777, 2017). "First, presumably through the inhibition of c-MET/EGFR-dependent cell proliferation, overexpression of miR-206 inhibited tumor growth in SKOV3-inoculated nude mice." (PMID 29291022, 2017). "Next, multivariable regression analysis demonstrated that EGFR CNG in female patients and CNG of HER3 and HER4 in male patients were still negatively associated with tumor grade." (PMID 29190914, 2017). "Critically, we observe significantly less staining of MATN2 and EGFR in the plasma membranes of the cells in the LOX-depleted tumours than in the cells of shRNA control tumours." (PMID 28416796, 2017). "Patient 03LSM exemplifies how tumor monitoring through liquid biopsy can open up new perspectives for the use of new therapies, anti-EGFR re-challenge, or even N-of-1 trials." (PMID 28947971, 2017). "It was also shown that a combination of buparlisib with the anti-EGFR monoclonal antibody cetuximab exerts a synergistic effect on tumor inhibition in wild-type or PIK3CA mutant HNSCC cell lines as well as in a xenograft model of HNSCC." (PMID 28108737, 2017). "In this review, we focus specifically on the crosstalk of EGFR- and EGFRvIII with pathways leading to increased tumor invasion and angiogenesis." (PMID 28629170, 2017). "Western Blotting analysis performed on tumor lysates at the end of the experimental regimen showed that EGFR protein was lost in RA-treated xenografts." (PMID 28684780, 2017). "In contrast, other findings have demonstrated that Src is involved in enhancing tumor cell invasion and that the interaction is not only exclusive to EGFRvIII but includes interaction with EGFR." (PMID 28629170, 2017). "The small molecule inhibitor lapatinib, which inhibits EGFR and HER2, associated with regorafenib showed a greater anti-tumor activity than the compound alone in xenograft models of CRC associated with a relevant reduction of angiogenesis." (PMID 29270405, 2017). "The tumor growth of KYSE960 cells was significantly suppressed by all groups treated with anti-EGFR antibodies compared with the group treated with saline (P < 0.001)." (PMID 28038457, 2017). "Together, these findings point towards an immune microenvironment mediated regulation that gives rise to intratumoral heterogeneity of EGFR signalling activity in tumour cells." (PMID 28166195, 2017). "Their mathematical models predict that the binding affinity (KD) for anti-EGFR antibodies should be in the range of 10−8 M–10−9 M to maximize tumor cell targeting while minimizing normal cell toxicity." (PMID 28912497, 2017).
tumor (continued). "Direct comparison with 89Zr-labelled anti-EGFR antibody cetuximab demonstrated that 89Zr-DFO-Z EGFR:2377 provided appreciably higher tumour-to-blood, tumour-to-liver, and tumour-to-bone ratios." (PMID 28729680, 2017). "Both these pathways are major downstream pathways of EGFR and can be blocked by EGFR inhibitors, resulting in tumor cell apoptosis." (PMID 28002810, 2017). "This extends the previous observation that MEDI3622 exerts it’s anti-tumor effect, in part, by modulating non-EGFR pathways." (PMID 29029414, 2017). "Activation of EGFR thereby exerts a protective function against DNA damage and promotes tumour cell survival." (PMID 29069805, 2017). "In this study, the co-delivery of Cet and PTX by ND enhances the mitotic catastrophe and tumor inhibition in the EGFR-expressed CRC." (PMID 28852020, 2017). "EGFR mutation status in plasma samples were tested with ADx-SuperARMS EGFR assay and tumor tissue samples were tested with ADx-ARMS EGFR assay." (PMID 28829813, 2017). "Our study presents for the first time that nimotuzumab was able to kill EGFR+ tumor cells by NK cell-mediated ADCC." (PMID 28674498, 2017). "Our results reveal that ENb-TRAIL is directly involved in activating DRs in addition to blocking EGFR thereby priming tumor cells for DR mediated apoptosis." (PMID 28572590, 2017). "Treatment with an antiplatelet agent or podoplanin-neutralizing antibody depressed the growth of an LSCC tumour xenograft via suppression of EGFR phosphorylation." (PMID 28642617, 2017). "In these studies (including our study), 155 patients were detected as cfDNA EGFR M+ and tumor-tissue EGFR M-, among a total of 3834 patients." (PMID 28052016, 2017). "In preclinical studies, afatinib and dacomitinib are effective to tumor harbouring T790M mutation and wide-type (WT) EGFR, although the IC50 is 10–500 fold higher than EGFR sensitive mutation alone." (PMID 29163853, 2017). "The sole responder in a phase II trial was a patient with EGFR amplification, and patients with higher tumour EGFR expression showed significantly longer survival." (PMID 28059068, 2017). "Eight patients underwent re-biopsy after tumor progression during EGFR-TKI, allowing a comparison between tissue and cftDNA." (PMID 26799287, 2017). "Taken together, these data indicate that the radiocobalt-labelled DOTA-ZEGFR:2377 demonstrated the best tumour-to-non-tumour ratios among all pre-clinically tested affibody-based agents for imaging of EGFR." (PMID 28729680, 2017). "Our study first revealed the location of tumour-secreted EGFR in target organs, explaining how membrane receptors can be transported between cells." (PMID 28393839, 2017). "Several retrospective analyses and meta-analyses have now shown that for right-sided tumours the anti-EGFR antibodies have very poor efficacy compared to bevacizumab." (PMID 28386297, 2017). "We demonstrate that in BL2 TNBC, NO activation of the EGFR/ERK signaling pathway plays a direct role in the development of a pro-inflammatory phenotype that increases tumor cell invasive capacity." (PMID 29113326, 2017). "The study also evaluated the frequency of EGFR and KRAS mutations in the adenocarcinoma tumor cell line with LLC cells." (PMID 29285236, 2017). "Although the prognostic or predictive function of EGFR expression in patients with NSCLC remains controversial, some researches have suggested that upregulation of EGFR expression is related to tumor establishment and spread and poor prognosis in NSCLC." (PMID 27823977, 2017). "AQP5 mediates proliferation and migration of tumor cells through the EGFR/ERK/p38 MAPK signaling pathway." (PMID 28404978, 2017). "We have identified that miR-34a acted as an important tumor suppressor in NSCLC with EGFR as a novel target, both in vitro and in vivo." (PMID 28825720, 2017). "Our model suggests that the EGF/EGFR/arginase II pathway represents a potential therapeutic target to prevent hypoxia induced proliferation in tumor cells." (PMID 28330951, 2017).